INS (insulin)
Diseases named in the same sentence as INS in open-access papers (continued):
Sharing a sentence is not in itself a finding about the gene and the disease.
Insulin resistance (continued). "It lowers blood glucose concentrations in diabetic patients, stimulates insulin production and its signal transduction, lessens endoplasmic reticulum stress, and attenuates inflammation and insulin resistance via PPAR-δ and NFκB-mediated signaling pathways." (PMID 39125340, 2024). "Adgrl1VMH-deficient mice show reduced physical activity, high lean mass and normal insulin-mediated glucose uptake in the skeletal muscle, while the liver and adipose tissue exhibit insulin resistance." (PMID 37712955, 2024). "The results of our study suggest that SIT treatment results in decrease in the markers for insulin resistance and increase in the markers for insulin sensitivity." (PMID 39074126, 2024). "Insulin resistance (IR), or decreased insulin sensitivity, is defined as ineffective insulin activity in peripheral tissues, leading to a subsequent state of hyperinsulinemia with impaired lipid and glucose regulation." (PMID 40071249, 2024). "Insulin resistance is a condition characterized by reduced biological activity of insulin, leading to an increase in insulin secretion to compensate for its diminished function." (PMID 38449844, 2024). "In non-diabetic cases the serum levels of SHBG correlated with serum insulin and insulin resistance." (PMID 39014506, 2024). "Palmitate, a common dietary saturated free fatty acid, has been found to directly impair insulin signaling and induce insulin resistance in cultured myotubes and hepatocytes." (PMID 38611884, 2024). "Chronic stress mice had higher fasting insulin levels and exhibited insulin resistance and glucose tolerance phenotypes." (PMID 38615060, 2024). "In humans, a decrease in the ratio of insulin levels in CSF compared to serum is noticed in cases of whole-body insulin resistance." (PMID 38534454, 2024). "Another study involving 2,403 Korean participants aged 70-84 found that men with high insulin resistance assessed by HOMA-IR had a significantly higher prevalence of sarcopenia compared to insulin-sensitive individuals." (PMID 39247923, 2024). "By definition, insulin resistance (IR) is a state of reduced response to insulin of target tissues with normal or elevated serum insulin levels and is the reciprocal of insulin sensitivity." (PMID 38398863, 2024). "Key outcomes included fasting blood sugar (FBS), postprandial blood sugar (PPBS), glycated hemoglobin (HbA1c), fasting insulin, insulin resistance (HOMA-IR), GLP-1 levels, lipid profile, and quality of life." (PMID 39835082, 2024). "In normal pregnancy, beta cell proliferation and insulin secretion are physiologically increased to accommodate exacerbated insulin resistance." (PMID 39835257, 2024). "Hepatic insulin resistance can be improved by either eliminating or depleting miR-29 in models of insulin disarray and type 2 diabetes." (PMID 38539937, 2024). "We observed a significant main effect of insulin resistance in the suppression of Ppargc1a expression, which showed pairwise difference between insulin-resistant cells and insulin-sensitive cells at 20 mM BCAA." (PMID 39057712, 2024). "Metformin has been defined as an insulin sensitizer, leading to a reduction in insulin resistance and therefore optimizing cellular glucose uptake, mainly in skeletal muscle, leading to a reduction in plasma glucose and insulin plasma values." (PMID 38610965, 2024). "In T2DM, elevated reactive oxygen species (ROS) levels decrease insulin sensitivity, leading to insulin resistance." (PMID 38390207, 2024). "Insulin resistance development in this population cannot be fully explained by hyperglycemia because many T1DM patients continue to have insulin resistance even when their glycemia is managed with aggressive insulin therapy." (PMID 39768947, 2024). "Reduced sensitivity of tissues to insulin (insulin resistance) results in the inability of glucose isolated by meal consumption to be absorbed into tissues in combination with insulin." (PMID 39796443, 2024).
Insulin resistance (continued). "A total of 99 patients with SCZ were recruited, and fasting glucose, fasting insulin, the insulin resistance index (HOMA-IR), and sex hormones were measured." (PMID 38549523, 2024). "At the core of the pathophysiology of metabolic syndrome, obesity is insulin resistance, a state in which the cells of the body exhibit reduced sensitivity to insulin, resulting in increased blood glucose levels." (PMID 39574946, 2024). "Insulin resistance (IR) characterizes reduced sensitivity and responsiveness to insulin’s action, often manifesting several years prior to the onset of diabetes." (PMID 38664804, 2024). "HOMA-IR reflects the degree of insulin in the patient, with higher values suggesting higher levels of insulin resistance." (PMID 40777932, 2024). "In the present study, children and adolescents with obesity but normal insulin sensitivity seem to be protected against alterations in glucagon and incretin secretion compared to individuals with insulin resistance." (PMID 38087928, 2024). "Insulin resistance is a characteristic of metabolic disorders and is defined as impaired insulin absorption and glucose utilization." (PMID 39076779, 2024). "Another consequence of the tissue’s insulin resistance is that insulin is unable to encourage glucose from entering the adipocyte and becoming oxidized." (PMID 38613048, 2024). "Berberine, recognized for its antidiabetic properties, has been shown to lower blood glucose levels, enhance insulin secretion, and diminish both glucose tolerance and insulin resistance through the activation of the AMPK pathway." (PMID 39407506, 2024). "These metabolites were deposited into nonadipocytes, leading to a cascade of metabolic changes and abnormalities in cytokine expression and consequently inhibiting insulin signaling pathways and exacerbating insulin resistance." (PMID 40302954, 2024). "It is possible that a higher insulin dose overcomes vascular insulin resistance and results in a beneficial effect." (PMID 39195275, 2024). "The DDQ-index was significantly inversely associated with fasting insulin, 2 h post-meal insulin, the incremental AUC of glucose during the total 4 h mixed meal test, and the HOMA index for insulin resistance." (PMID 39458507, 2024). "Insulin resistance, characterized by impaired insulin‐mediated regulation of glucose metabolism in tissues, was usually caused by disturbances in downstream signalling pathways of insulin." (PMID 39474649, 2024). "Desulfovibrio is also positively correlated with increases in fasting insulin, which can lead to insulin resistance." (PMID 38257161, 2024). "Type 2 diabetes (T2D) is a chronic metabolic disorder characterised by impaired response of insulin-sensitive tissues to insulin (insulin resistance), leading to hyperglycaemia and, ultimately, insulin secretion deficits." (PMID 38802514, 2024). "The metformin treatment in fructose-fed rats promoted glucose, insulin, Homeostasis Model Assessment of Insulin Resistance Index (HOMA-IR), and Triglyceride (TG) values in both sexes." (PMID 38884844, 2024). "Skeletal muscle plays a crucial role as a primary target for insulin action, and the decline in muscle mass and strength can potentially worsen insulin resistance." (PMID 38962441, 2024). "Insulin resistance, characterized by elevated insulin levels in the bloodstream and decreased cell responsiveness to insulin, affects not only overweight but also lean women." (PMID 38671840, 2024). "“Insulin resistance is defined as an impaired response to insulin stimulation in peripheral tissues, which leads to increased peripheral insulin levels”." (PMID 39518747, 2024). "In ESKO-administered obese mice, serum insulin levels and insulin resistance were significantly decreased in comparison with those of the Model group." (PMID 39519447, 2024).
Insulin resistance (continued). "Insulin resistance (IR), also known as reduced insulin responsiveness, is a common marker of type 2 diabetes, hypertension, lipid metabolic issues, and even cardiovascular disease." (PMID 38463431, 2024). "Our data also align with previous studies that used IVGTT to measure insulin resistance or insulin sensitivity." (PMID 37914981, 2024). "The degree of insulin resistance and the amount of circulating insulin are strongly correlated in most patients with prediabetes and insulin resistance." (PMID 38398039, 2024). "Aging accelerates changes and reduces insulin sensitivity due to the insufficient compensation of beta cell function during the process of increasing insulin resistance." (PMID 39062777, 2024). "Insulin resistance is clinically defined as the biological effect of a given concentration of insulin that is lower than expected." (PMID 39769097, 2024). "Insulin resistance, insulin signaling pathway, and peroxisome proliferators-activated receptors (PPAR) signaling pathway were significantly enriched." (PMID 38441470, 2024). "In a clinical setting, insulin resistance is commonly evaluated using hyperinsulinemic-euglycemic clamp test and fasting insulin (e.g., HOMA-IR)." (PMID 38812015, 2024). "This accumulation results in reduced insulin signaling, increased proinflammatory cytokines, and the exacerbation of brain insulin resistance, neuronal apoptosis, and neuroinflammation." (PMID 38379904, 2024). "As a result of this study, positive effects of GSE on average insulin level, insulin resistance, lipid profile, blood pressure and severity of hepatic steatosis were seen in patients with NAFLD." (PMID 38755622, 2024). "Insulin resistance, which is characterized by a reduced sensitivity to insulin in regulating blood glucose levels, is the primary pathological feature of type 2 diabetes mellitus." (PMID 38397797, 2024). "DM1-related changes in insulin signaling have been reported in ∼30 clinical studies, and insulin resistance is a key phenotype due to, at least partially, the aberrant regulation of insulin receptor (INSR) splicing." (PMID 38760841, 2024). "There is considerable evidence that exogenous glucocorticoids induce both insulin secretion and insulin resistance in chickens." (PMID 38473137, 2024). "Obese individuals develop insulin resistance, which is characterized by impaired insulin action in the liver and reduced glucose uptake in fat and muscle." (PMID 38339160, 2024). "Insulin levels and HOMA were not different between men and women after VLCKD, thus apparently excluding a significant effect of gender on insulin levels and insulin resistance." (PMID 38794646, 2024). "As expected, insulin-stimulated lipogenesis was completely blocked in Nrg4 KD adipocytes, in keeping with previous data on insulin resistance in this model." (PMID 39519269, 2024). "The prolonged hyperglycemic state resulting from decreased sensitivity to insulin in insulin resistance (IR) can initiate heightened glycosylation." (PMID 38741118, 2024). "Strawberry ameliorates peripheral insulin resistance, reduces α-amylase and α-glucosidase activity, and increases glucose-stimulated insulin release." (PMID 39519546, 2024). "This phenomenon is referred to as selective insulin resistance or pathway-selective insulin responsiveness." (PMID 38397072, 2024). "Its levels are inversely related to insulin and insulin resistance in obesity and decreased by high glucose and insulin levels." (PMID 39246394, 2024). "Additional tests include determination of insulin sensitivity and/or insulin resistance with the technologies available in the clinics." (PMID 39472276, 2024). "Recent scientific studies demonstrate that a high level of plasma C 16:0 increases the cellular uptake of C 16:0, leading to insulin signaling inhibition and the development of insulin resistance." (PMID 38459494, 2024).
Insulin resistance (continued). "A negative correlation has been demonstrated between serum Ome concentration and BMI, as well as insulin resistance index, leptin, plasma glucose and insulin." (PMID 39064727, 2024). "Obese females had elevated blood insulin and glucose levels, indicating the development of insulin resistance, which was more pronounced in 7CafD females." (PMID 39596499, 2024). "The main mechanisms leading to T2DM are a complex combination of insulin resistance (IR) and initial hyperinsulinemia, followed by progressive dysfunction of pancreatic β-cells to produce insulin." (PMID 39685901, 2024). "Obesity often leads to insulin resistance and hyperinsulinemia, which increase levels of insulin and IGF-I, promoting cell proliferation and inhibiting apoptosis." (PMID 38999846, 2024). "Insulin resistance and impaired beta-cell secretion of insulin both contribute to hyperglycemia-induced OxS and diabetic complications." (PMID 38397782, 2024). "This is because IGF-I secretion depends on the direct action of bST, while the insulin response to bST is a more intricate indirect effect (hyperglycemia and insulin resistance)." (PMID 38612336, 2024). "It has been shown to play a role in repairing inflammatory damage, improving the lipid profile, increasing insulin sensitivity, and reducing insulin resistance." (PMID 39190657, 2024). "Insulin resistance can be induced by oxidative stress via the interference with insulin signal transmission and deregulation of adipokines, as well as inflammation—occurring in the course of both insulin resistance and oxidative stress." (PMID 38792339, 2024). "In these mice, the islets of Langerhans are hypertrophied, which leads to an increase in insulin content and a general state of insulin resistance." (PMID 38444587, 2024). "Nicotine exposure can also lead to abnormalities in normal insulin signaling pathways, potentially exacerbating insulin resistance." (PMID 38779450, 2024). "Decreased responsiveness of tissues to insulin results in insulin resistance (IR), a multifaceted pathological state marked by diminished sensitivity." (PMID 38920999, 2024). "Exosomes from M1 macrophages induce insulin resistance in adipocytes, whereas M2 macrophage-derived exosomes improve insulin sensitivity and glucose tolerance." (PMID 39220365, 2024). "Insulin resistance occurs when cells in the body grow resistant to insulin’s actions, resulting in high blood sugar levels." (PMID 38645750, 2024). "It has been established that chronic hyperinsulinemia in insulin resistance implicates both β-cell dysfunction and impaired insulin clearance." (PMID 39640841, 2024). "Insulin is an essential negative regulator of synovial inflammation and catabolism, so the development of insulin resistance in obese individuals would impair insulin’s ability to suppress the production of inflammatory and catabolic mediators that promote OA." (PMID 39200096, 2024). "Specifically, chronic low-grade inflammation contributes to organ dysfunction and tissue damage, which can promote insulin resistance and impaired insulin secretion." (PMID 38541168, 2024). "Due to severe insulin resistance, many patients with lipodystrophy syndromes will need large amounts of insulin to control their blood glucose." (PMID 38952397, 2024). "The study highlights that under conditions of insulin resistance, the endothelium's sensitivity to insulin diminishes, resulting in impaired vasodilation." (PMID 39744210, 2024). "Animal studies have revealed that arecoline can induce insulin resistance by impairing insulin signaling and glucose uptake in skeletal muscle cells." (PMID 38894993, 2024). "The observed induction in the phosphorylation level of the insulin-signaling protein by the decoction extracts in the insulin-resistant L6 myotubes suggested that C. prophetarum can improve insulin resistance in T2DM." (PMID 39795155, 2024).
Insulin resistance (continued). "A recent study reported that insulin impacts the BBB endothelium and insulin resistance is linked to a dysfunctional BBB structure and components using RNA sequencing, functional annotation, and gene ontology." (PMID 39063010, 2024). "Type 2 diabetes is a chronic disease characterized by insufficient insulin release from pancreatic β cells or insulin resistance." (PMID 38805166, 2024). "Significant differences were observed in fasting blood glucose, plasma insulin levels and insulin resistance in patients with type II diabetes after an 8-week AT intervention at an intensity of 60% compared to a control group." (PMID 38440349, 2024). "It is characterized by insulin resistance in peripheral tissues and impaired insulin secretion due to progressive pancreatic β-cell dysfunction and loss of β-cell mass." (PMID 39560873, 2024). "Insulin resistance (IR) is usually considered a systemic response or reduced sensitivity to insulin effects." (PMID 39719978, 2024). "Modern scientific studies have further elucidated its antidiabetic mechanisms, which involve reducing insulin resistance, enhancing insulin secretion, inhibiting glucose absorption and reabsorption, and improving insulin sensitivity and metabolic processes." (PMID 39273546, 2024). "Impaired insulin secretion and insulin resistance also result in altered lipid metabolism with increased levels of free fatty acids." (PMID 39768436, 2024). "Insulin resistance is a state in which the body’s sensitivity and response to insulin are reduced, resulting in the inability of insulin to efficiently transport glucose into cells, causing metabolic abnormalities such as hyperglycemia." (PMID 38184598, 2024). "Calcineurin inhibitors, particularly tacrolimus, show deleterious effects on pancreatic β-cells, leading to their apoptosis and thus reduced insulin secretion, but also the induction of insulin resistance." (PMID 39204092, 2024). "TNF-α impairs insulin action by activating JNK and IKKβ pathways, disrupting insulin signaling, while IL-1β and IL-6 exacerbate insulin resistance by inhibiting receptor functions and glucose uptake." (PMID 39458518, 2024). "Another notable endocrine changes observed in peripartum cows is the reduced secretion of insulin and the development of insulin resistance." (PMID 39881718, 2024). "Insulin resistance impairs glucose metabolism and forces pancreatic β cells to increase insulin production, leading to hyperinsulinemia and β cell hypertrophy." (PMID 39519540, 2024). "RAAS activation not only induces systemic insulin resistance but also affects cardiac insulin signaling pathways, including the mTOR–S6K1 pathway." (PMID 39125938, 2024). "Hyperinsulinemia compensates for insulin resistance as a consequence of overstimulation of non-insulin-sensitive tissues, such as the ovaries." (PMID 38348417, 2024). "In this context, we utilized a TNF-α-based cellular model to induce insulin resistance (IR) due to its established role as a pro-inflammatory cytokine that disrupts insulin signaling." (PMID 39627194, 2024). "As a result, increased serine phosphorylation of IRS-1 reduces insulin-stimulated threonine phosphorylation, leading to insulin resistance and type 2 diabetes (T2D) development." (PMID 39339244, 2024). "During the diabetic state (Type 2), these receptors are less sensitive to insulin and this pathological condition is called insulin resistance." (PMID 38543143, 2024). "When insulin resistance occurs, the body needs to produce more insulin to compensate, leading to a condition called hyperinsulinemia." (PMID 39188978, 2024). "It is known that prolonged exposure to excessive glucose levels inhibits the production of insulin and is correlated with the expansion of peripheral insulin resistance." (PMID 38926327, 2024).